PTH (parathyroid hormone)
Diseases named in the same sentence as PTH in open-access papers (continued):
Sharing a sentence is not in itself a finding about the gene and the disease.
renal failure (187 papers, 2007 to 2026). "Although the target ranges for PTH in current clinical guidelines are mainly based on its associations with mortality, the primary target organ of PTH is bone in the setting of kidney failure." (PMID 39430172, 2024). "We had the opportunity to collaborate with this group and were able to show that in a manner analogous to the role of PTHrP in malignancy, PTH also induces adipose tissue browning and causes cachexia in kidney failure." (PMID 36977891, 2023). "In patients with kidney failure, the major target organ for PTH is the bone, but elevated PTH is also associated with mortality presumably through skeletal and nonskeletal mechanisms." (PMID 36977891, 2023). "This step is tightly regulated by calcium, PTH levels, and calcitriol itself, which explains why renal insufficiency also results in deficient calcitriol levels." (PMID 36364774, 2022). "Very low levels of PTH have been associated with poor outcomes, and it is possible that different patients with renal failure have different optimal levels of PTH after PTX5,6,57." (PMID 35179187, 2022). "While skeletal responsiveness to PTH is reduced in patients with renal failure, serum urate had recently been associated with increased BMD and a positive relationship between the change in serum urate and change in BMD with thiazides was reported." (PMID 34722890, 2021). "MicroRNAs (miRNAs) have been identified as useful biomarkers in various diseases, and the aim of this study was to identify miRNAs associated with parathyroid hormone level in peritoneal dialysis (PD) patients." (PMID 28152049, 2017). "Increased PTH concentrations are associated with increased mortality rates, vascular and valvular calcification, renal failure, heart failure, and cardiovascular disease." (PMID 25734565, 2015). "Similarly, in two studies of patients undergoing kidney dialysis, increased endogenous PTH was associated with a decrease in HR variability, implicating PTH in the ANS dysfunction that occurs in individuals with kidney failure." (PMID 32194439, 2020). "Randomized trials of vitamin D supplementation on parathyroid hormone (PTH) levels in adults with kidney failure (divide by 2.5 to convert from nmol/l to ng/ml)." (PMID 39875204, 2025). "In this instance, low blood levels of vitamin D and calcium found in renal failure stimulate the parathyroid glands to produce consistently high levels of PTH." (PMID 38484798, 2024). "Substances such as urea, guanidine succinate, parathyroid hormone, phenol, and tryptophan accumulate in patients with renal failure as clearance decreases." (PMID 39685647, 2024). "PTH, serum calcium and phosphate are independently correlated with progression to kidney failure in CKD patients staging from as early as G2 up to G5 end-stage disease." (PMID 38785509, 2024). "For patients suffering from insufficiently controlled HPT or complications as renal insufficiency or calcifications a replacement therapy with recombinant human (rh) PTH is available." (PMID 38027217, 2023). "Mineral bone disorders are often seen in patients with renal failure, mainly due to their advanced age, abnormal metabolism of calcium, phosphate, vitamin D and parathyroid hormone, soft tissue calcification and abnormal bone remodelling and mineralisation." (PMID 37111132, 2023). "It has been elucidated that parathyroid hormone (PTH) increases more in higher stages of renal failure." (PMID 37507659, 2023). "Blood urea nitrogen, creatinine, phosphorus, potassium, and whole parathyroid hormone were significantly increased, whereas 1,25-dihydroxyvitamin D3 was decreased in both groups, all of which were changes commonly observed in renal failure patients." (PMID 37700060, 2023). "When patients reach kidney failure, circulating levels of PTH and FGF23 increase 5- to 10-fold and 10- to 50-fold above normal, respectively." (PMID 36977891, 2023).
renal failure (continued). "As a potential explanation for these observations, a recent breakthrough revealed a key role of PTH in the pathogenesis of wasting in kidney failure." (PMID 36977891, 2023). "The parathyroid hormone level of patients with severe acute renal failure in the control groups was (88.5 ± 6.7) pg/L, and the renin level of patients with severe acute renal failure in the control groups." (PMID 37547338, 2023). "The parathyroid hormone level of patients with severe acute renal failure in the observation groups was (46.6 ± 5.8) pg/L." (PMID 37547338, 2023). "In turn, renal insufficiency combined with an increase in PTH levels seems to affect serum Glu-OC concentrations in our rats with CKD." (PMID 36235734, 2022). "Bone mineral disorder is a potential mechanism of PH pathogenesis in CKD, and one study showed positive correlations between echocardiographically estimated sPAP and calcium, phosphate and PTH in peritoneal dialysis patients." (PMID 36275815, 2022). "They identified that synbiotic therapy reduced inflammation and renal insufficiency, along with a parallel increase of PTH levels." (PMID 33514340, 2021). "Confirming previous in vivo and clinical studies of patients with renal insufficiency, we observed a positive association between FGF23 and PTH." (PMID 33640873, 2021). "Lanthanum hydroxide, a new phosphate binder, delayed the progression of kidney failure, suppressed the development of vascular calcification; decreased serum PTH and FGF23 levels, and significantly suppressed serum phosphorus." (PMID 33928079, 2021). "Subsequently, parathyroid hormone was found to be elevated (378.5 pg/mL, reference range 8.5–72.5 pg/mL), suggesting that renal failure was more long-standing." (PMID 32843431, 2020). "A general finding in renal failure is the resistance produced due to the calcemic mechanism present in PTH and secondary hyperthyroidism." (PMID 32963524, 2020). "The studies revealed that the cerebral calcium levels raise with the PTH effect in renal insufficiency." (PMID 31126169, 2019). "Both CKD patients and experimental animal models of kidney failure show increased serum PTH and FGF23 levels." (PMID 30393837, 2019). "Further studies showed that this failure of PTH to maintain blood 1,25(OH)2D levels was associated with decreased blood levels of IGF-1, increased blood levels of FGF-23, and kidney failure." (PMID 31791247, 2019). "Since vitamin D is useful in controlling excessive secretion of parathyroid hormone in kidney failure, replacement therapy is routine in hemodialysis units." (PMID 30134544, 2018). "In fact, KTx patients often have high PTH levels, an altered bone status and an abnormally high occurrence of fractures mainly as the consequence of their previous (long) history of renal failure." (PMID 28554998, 2017). "Despite elevated blood FGF23, both kidney failure models augmented renal Cyp27b1 expression, probably due to the observed increase in PTH." (PMID 26566277, 2015). "In concert with the phosphaturic effects of FGF23 and PTH, both kidney failure models displayed a reduced renal expression of NaPi2a and PIT2, the principal renal type II and III sodium-dependent Pi transporters, respectively." (PMID 26566277, 2015). "AMG 416 was administered as a single intravenous (IV) bolus in a severe, acute model of renal insufficiency (the “1K1C” model) and plasma parathyroid hormone (PTH) and serum calcium levels were monitored for 24 hours." (PMID 24884838, 2014). "Four weeks after induction of renal insufficiency, PTH-KL−/− mice exhibited sHPT just like their wild-type littermates did." (PMID 24348262, 2013). "This is especially a problem in patients with renal failure, since inactive carboxyl-terminal PTH fragments accumulate in these patients, leading to falsely elevated results in the assay." (PMID 22792251, 2012). "GFR is a well known determinant of PTH and increases in PTH occur early in the course of renal insufficiency." (PMID 22867424, 2012).
renal failure (continued). "Third generation PTH assay was developed when it became apparent that patients with renal failure sometimes have intact PTH levels out of proportion to the level of bone disease even when 2nd generation assays were used." (PMID 22792251, 2012). "The evolution of circulating PTH molecular forms during sHPT due to renal failure (RF) is different, mainly because C-PTH fragments are cleared by the kidneys." (PMID 21747853, 2011). "Of note, in renal failure PTH has a permissive role on the activation of interstitial fibroblasts in vitro and in vitro." (PMID 21298056, 2011). "Plasma FGF-23 and intact parathyroid hormone (PTH) levels were measured in 12 patients with acute kidney injury and 8 control subjects." (PMID 21906363, 2011). "As renal failure progresses, ensuing abnormal parathyroid hormone (PTH) secretion results in deterioration of trabecular microarchitecture, thinning of cortical bone, and increased cortical porosity." (PMID 17622566, 2007). "However, removing those with low eGFR also excises the patients with elevated PTH levels due to kidney failure." (PMID 39865206, 2025). "As renal failure progresses, usually with a GFR ≤ 60 mL/min/1.73m2, changes occur in serum concentrations of calcium, phosphate, vitamin D, and parathyroid hormone (PTH), which are associated with vascular and soft tissue calcifications, as well as alterations in bone remodeling." (PMID 39404444, 2024). "However, due to the reduced clearance of iPTH caused by renal insufficiency in SHPT patients and the cross-reactivity of complete and partial PTH, the criteria for IOPTH to determine the success and prognosis of SHPT surgery are still controversial." (PMID 37197419, 2023). "The results of the study showed that although the reduction rates of Io-PTH in the group of patients with renal insufficiency were lower, but by changing the endpoint for Io-PTH evaluation for surgical success from 10 to 15 min, the diagnostic accuracy of this technique will increase from 89 to 95%." (PMID 37231458, 2023). "Among patients with kidney failure, bone is recognized as the principal target of PTH." (PMID 36977891, 2023). "Clinical data show that after replacement therapy and hemodialysis in patients with severe acute renal failure in the observation group, the levels of parathyroid hormone, renin, and quality of life were all improved, with an improvement rate of 9.47%, which has certain promotional value." (PMID 37547338, 2023). "Thus, the observation groups with severe acute renal failure had a higher parathyroid hormone level than the control groups." (PMID 37547338, 2023). "Obviously, the values of PTH as well as hypovitaminosis D could be influenced by aging and renal insufficiency." (PMID 35742610, 2022). "The immoderate secretion of PTH in patients with renal failure leads to high bone turnover." (PMID 34098899, 2021). "Previous studies have shown that PTH fragment accumulation depends on the degree of kidney failure." (PMID 34136780, 2021). "However, based on analyses of PTH kinetics in patients with renal insufficiency, cross-reacting PTH fragments are widely eliminated within the first postoperative week." (PMID 30519885, 2018). "Thus, PTH and FGF23 have been implicated as key players in mediating the observed changes in skeletal metabolism during kidney failure." (PMID 29394885, 2018). "While recent guidelines focus primarily on treating renal failure populations, work from Levin and colleagues describes early changes in mineral metabolism, particularly parathyroid hormone (PTH) concentrations, that are evident in individuals with only moderate kidney disease." (PMID 25918645, 2015). "One possibility is that renal failure leads to skeletal resistance to PTH, and decreases in PTH signalling activity might result in increased production of sclerostin in CKD patients." (PMID 25053944, 2014).
renal failure (continued). "In summary, patients received high rates of serum creatinine surveillance following hospitalization complicated by acute kidney injury, but rates of monitoring for quantitative proteinuria, PTH, and phosphorus measurement were low among the patients, regardless of AKI severity." (PMID 25117447, 2014). "Notably, serum FGF23 levels were increased by approximately 50-fold in both PTH-KL−/− and wild-type mice with renal failure compared to mice with preserved renal function." (PMID 24348262, 2013). "To test whether parathyroid function is different in PTH-KL−/− mice under conditions of renal insufficiency, we induced renal failure using an adenine-based protocol." (PMID 24348262, 2013). "This is believed to contribute to the PTH resistance observed in renal failure experimentally." (PMID 21747853, 2011). "This could be a result of low parathyroid hormone, renal failure, or excessive vitamin D3 dosage." (PMID 40920750, 2025). "The role of PTH in relation to renal insufficiency in HPT remains unclear." (PMID 38027217, 2023). "Hence, io-PTH measurement can also be used in patients with renal insufficiency." (PMID 37231458, 2023). "Therefore, renal insufficiency was not considered the primary cause of the elevated PTH." (PMID 41561737, 2025). "This is critical as PTH acts as an important marker for CKD; excess PTH can contribute to kidney failure, indicating renal impairment when elevated." (PMID 39484207, 2024). "Patients with PC are often characterized by markedly elevated serum calcium and parathyroid hormone (PTH) who typically present with metabolic complications, including renal failure, bone disease, pancreatitis, cardiac arrhythmia, and occasionally a neck mass." (PMID 35250443, 2022). "The degree of renal failure determines the amount FGF23 and PTH required to excrete an excess of P intake." (PMID 33498560, 2021). "Treatment with 0.2 g kg–1 lanthanum hydroxide decreased serum phosphorus, PTH, and FGF23 levels, and delayed the development of renal failure." (PMID 33928079, 2021). "We chose a quite severe, acute model of renal insufficiency (the 1 kidney removal and 1 clip, or “1K1C” model) to examine the efficacy of a single IV dose of AMG 416 vs oral cinacalcet in the presence of elevated PTH and serum creatinine." (PMID 24884838, 2014). "In addition to treatment modality, a comprehensive analysis of age, gender, duration of dialysis, history of renal insufficiency, comorbidities, and baseline levels of Hb, ALB, BNP, PTH, Ca, P, β-CTX, PINP, and BAP showed that only increasing age significantly increased the risk of mortality." (PMID 39713805, 2024). "All patients had blood calcium corrected for albumin level (total and ionized) assessed, and there were no cases of renal failure that may interfere with the assessment of PTH, calcemic or urinary electrolyte excretion." (PMID 37568342, 2023). "The authors of the Chronic Renal Insufficiency Cohort study, who analyzed risk factors for CVD and renal failure progression, demonstrated that the coexistence of DM among patients with CKD was independently related to higher levels of phosphate, PTH, and FGF23 compared with nondiabetic individuals." (PMID 35736431, 2022). "Based on our findings that the parathyroid glands of PTH-KL−/− mice retained calcium sensitivity and that sHPT developed similarly as in wild-type mice upon induction of renal insufficiency, we reasoned that the parathyroid response to FGF23 might also be preserved in PTH-KL−/− mice." (PMID 24348262, 2013). "Parathyroid hormone (PTH) was decreased (13.58 pg/mL) and there were high levels of urea (101.7 mg/dL) and creatinine (3.97 mg/dL), setting up a framework of acute kidney injury which lasted 2 months, not requiring renal replacement therapy." (PMID 32580697, 2020). "Our study investigated the negative effects of renal failure and its relationship with phosphorus, FGF23, PTH, sclerostin, and bone." (PMID 29394885, 2018).
renal failure (continued). "No patients had severe kidney failure (MDRD <15 mL/min); median PTH level was 27.3 ± 18.8 pg/mL (interquartile range 15.8–34.1) and mean albumin-adjusted total serum calcium was 8.9 ± 1 mg/dL." (PMID 30300540, 2018). "The effect of serum calcium level, kidney failure, or symptomatic treatment on BMD should be carefully interpreted in view of the limited choice of assessed parameters including 1,25 (OH)2D3, and the lack of serum PTH and phosphate levels." (PMID 40301993, 2025).